CNKSR1 (connector enhancer of kinase suppressor of Ras 1)
Description:
May function as an adapter protein or regulator of Ras signaling pathways.
Synonyms: CNK1; KSR; CNK
Tractability: Small molecule: a high-quality ligand is known. Antibody: its Gene Ontology location is reachable by antibodies, with high confidence; UniProt places it where antibodies can reach, with medium confidence. PROTAC: a small molecule that binds it is known.
Gene: Protein-coding gene on chromosome 1 (26,177,476 to 26,189,884, forward strand). Ensembl gene ENSG00000142675.
Subcellular location: Cytoplasm; Membrane
Subcellular location (Human Protein Atlas): Cytosol
Pathways (Reactome):
Disease: Paradoxical activation of RAF signaling by kinase inactive BRAF; Signaling by BRAF and RAF1 fusions; Signaling by RAF1 mutants; Signaling by high-kinase activity BRAF mutants; Signaling by moderate kinase activity BRAF mutants; Signaling downstream of RAS mutants
Signal Transduction: MAP2K and MAPK activation
Gene Ontology:
Molecular function: protein binding; protein-macromolecule adaptor activity
Biological process: cell surface receptor protein tyrosine kinase signaling pathway; enzyme-linked receptor protein signaling pathway
Cellular component: cell cortex; cell-cell junction; plasma membrane; cytoplasm; membrane
Genetic constraint (gnomAD): Loss-of-function variants: 84 observed, 93.81 expected, observed/expected ratio (o/e) 0.9, 90% interval 0.75 to 1.07. The upper end of that interval is the gene's LOEUF score, 1.07, which puts it in group 4 of 6, group 1 being the genes least tolerant of losing a copy. Missense variants: 812 observed, 914.37 expected, observed/expected ratio (o/e) 0.89, 90% interval 0.84 to 0.94. Synonymous variants: 351 observed, 368.59 expected, observed/expected ratio (o/e) 0.95, 90% interval 0.87 to 1.04.
Homologues: Orthologues: chimpanzee CNKSR1 (99% identical), macaque CNKSR1 (96% identical), pig CNKSR1 (81% identical), dog CNKSR1 (80% identical), rabbit CNKSR1 (77% identical), guinea pig CNKSR1 (76% identical), mouse Cnksr1 (76% identical), rat Cnksr1 (75% identical), tropical clawed frog cnksr1 (40% identical), zebrafish cnksr1 (37% identical), Drosophila melanogaster cnk (24% identical), Caenorhabditis elegans cnk-1 (18% identical). Paralogues in human: CNKSR2 (33% identical), CNKSR3 (19% identical), IPCEF1 (14% identical), SAMD3 (11% identical).
Diseases named in the same sentence as CNKSR1 in open-access papers:
CNKSR1 is named in the same sentence as 13 diseases in open-access papers, as found by Europe PMC text mining. Sharing a sentence is not in itself a finding about the gene and the disease. The quoted sentences say what the papers report.
breast carcinoma (4 papers, 2010 to 2021). "High protein expression of CNKSR1 was associated with poor prognosis for HER2-positive breast cancer patients." (PMID 34187934, 2021). "Expression profile of connector enhancer of kinase suppressor of Ras1 (CNKSR1) in human HER2-positive breast cancer tissues." (PMID 34187934, 2021). "The phosphorylation of Akt is positively regulated by CNKSR1 in basal-type breast cancer MDA-MB-231 cells." (PMID 34187934, 2021). "We next examined the protein expression of CNKSR1 in HER2-positive human breast cancer tissues." (PMID 34187934, 2021). "CNKSR1 was highly expressed in 80% of HER2-positive breast cancer tissues." (PMID 34187934, 2021). "Among the various breast cancer cell lines, we found that CNKSR1 was highly expressed in a HER2-positive breast cancer cell line, SKBR-3, and protein expression of CNKSR1 was low in MCF-7 (luminal-type), MDA-MB-231 (basal-type), and MDA-MB-453 (HER2-positive–type) cells." (PMID 34187934, 2021). "Our present results suggest that CNKSR1 serves as an oncoprotein by inactivating PTPRH, a tumor-suppressive EGFR phosphatase, in HER2-positive breast cancer cells." (PMID 34187934, 2021). "From a drug-discovery standpoint because inhibition of the PTPRH/CNKSR1 complex releases PPTRH leading to its activation, inhibitors of this PTPRH/CNKSR1 interaction could represent novel drugs for HER2-positive breast cancers." (PMID 34187934, 2021). "In a HER2/EGFR-double positive breast cancer cell line, SKBR-3, the overexpression of Myc-tagged or non-tagged CNKSR1 increased the phosphorylation of both EGFR and HER2, as well as cell proliferation." (PMID 34187934, 2021).
pancreatic cancer (3 papers, 2017 to 2022). "Using pancreatic tumor tissues from three independent cohorts, we aimed to evaluate the expression levels of CNKSR1 and its association with clinicopathological parameters and survival in pancreatic cancer." (PMID 28732488, 2017). "In addition, we attempted to determine whether CNKSR1 status might affect the survival difference associated with resection in pancreatic cancer patients." (PMID 28732488, 2017). "The expression of pERK was also correlated with CNKSR1 distribution (expression of the scaffold connector enhancer of kinase suppressor of Ras 1 (CNKSR1) is correlated with clinical outcome in pancreatic cancer)." (PMID 35409691, 2022). "CNKSR1 expression was correlated with the survival rate in pancreatic tumor patients and suggested to be an independent prognostic marker for survival." (PMID 35409691, 2022). "Immunohistochemical staining for CNKSR1 expression was performed on 120 specimens from three independent pancreatic cancer tissue registries, phospho-ERK levels were measured in 86 samples." (PMID 28732488, 2017). "In this correlative tissue study including independent pancreatic cancer tissue microarrays from different sources, CNKSR1 expression was found to be an independent marker of patient outcome." (PMID 28732488, 2017). "In this study, we examined the expression levels of the scaffolding kinase CNKSR1 in pancreatic cancer surgical resection specimens and evaluated their impact on clinical outcome, including overall survival (OS)." (PMID 28732488, 2017). "We consider validation of the CNKSR1 expression pattern used for the correlative outcome studies in the two independent cohorts of pancreas cancer surgical specimens a strength of the study." (PMID 28732488, 2017). "To examine if CNKSR1 expression is dysregulated in pancreas cancer we first compared CNKSR1 expression measured by intensity of immunostaining in 13 randomly chosen matched tumor and normal pancreatic tissues from the SEER Pancreatic Cancer TMA." (PMID 28732488, 2017). "Pancreatic tumors with nuclear in addition to cytoplasmic CNKSR1 staining (32/107) showed increased nuclear phospho-ERK expression compared to tumor with cytoplasmic CNKSR1 staining only (p = 0.017)." (PMID 28732488, 2017). "CNKSR1 may represent an additional prognostic marker in pancreatic cancer, and further validation in a larger cohort of recent patients is needed." (PMID 28732488, 2017). "Co-staining of matched SEER Pancreatic Cancer TMA specimens with p-ERK suggests a correlation between cellular distribution of CNKSR1 and nuclear p-ERK expression levels, possibly indicating regulation of MAPK pathway signaling less connected to absolute CNKSR1 expression levels." (PMID 28732488, 2017). "Thus, CNKSR1 expression status might capture unfavorable tumor biology for surgical resection for pancreatic cancer, and may aid in pre-operative treatment selection." (PMID 28732488, 2017). "We analyzed the expression levels of CNKSR1, a scaffold that influences MAPK/ERK pathway activity, in clinical pancreas cancer specimens and their impact on survival of patients with pancreatic cancer." (PMID 28732488, 2017). "In addition, the PH domain of CNKSR1 combines with mut‐KRAS to inhibit the growth of mut‐KRA cells, which can treat a variety of cancers, such as pancreatic cancer." (PMID 34541834, 2022). "To gain more insight into the mechanism of action and role of CNKSR1 in MAPK pathway regulation, we next measured expression levels of phospho-ERK in 86 matched cases of the SEER Pancreatic Cancer TMA previously evaluated and scored for CNKSR1 expression levels." (PMID 28732488, 2017). "However, to date all CNKSR1 analysis in the context of pancreatic cancer has been performed at a molecular level with no translational or clinically oriented application." (PMID 28732488, 2017).
colorectal cancer (2 papers, 2017 to 2021). A primary or metastatic malignant neoplasm that affects the colon or rectum. "CNKSR1 functions as an oncogene and drives anchorage-independent cell growth through RAF/MEK/ERK phosphorylation in K-Ras–mutated lung and colorectal cancers." (PMID 34187934, 2021). "In a colorectal cancer cell model, CNKSR1 has been shown to facilitate pro-apoptotic signaling via RASSF1A." (PMID 28732488, 2017).
lung adenocarcinoma (2 papers, 2022 to 2025). A carcinoma that arises from the lung and is characterized by the presence of malignant glandular epithelial cells. "In a separate study, the identical SunTag system (dCas9-multiGCN4 + ScFv-TET1CD) was employed to induce the expression of CARD9, SH3BP2, and CNKSR1 in A549 and 1–87 lung adenocarcinoma cell lines." (PMID 40650152, 2025).
autosomal recessive intellectual disability (1 paper, 2023). "Defects in CNKSR1 have been linked to syndromic autosomal recessive intellectual disability (ID)." (PMID 36855151, 2023).
ovarian carcinoma (1 paper, 2026). A malignant neoplasm originating from the surface ovarian epithelium. "This study aims to utilize multiomics and bioinformatics techniques to investigate the expression of the connection enzyme inhibitor Ras1 1 (CNKSR1) in ovarian cancer (OC) and its mechanism of action in the processes of tumor proliferation, invasion, and metastasis." (PMID 41971765, 2026).
cancer (9 papers, 2017 to 2024). A tumor composed of atypical neoplastic, often pleomorphic cells that invade other tissues. "The plasmalemmal localization of CNKSR1 as well as colocalization with K-Ras mutant at the plasma membrane was lost by treatment of K-Ras mutated cancer cells with PHT-7.3." (PMID 34187934, 2021). "CCDC88A is a key modulator of the AKT-mTOR signaling pathway and CNKSR1 promotes invasion of cancer cells through NFκB dependent signaling (Fritz and Radziwill, 2010)." (PMID 30042785, 2018). "One of the main functions of the scaffold protein CNKSR1 is the regulation of other cancer-related signaling pathways integrating output to different intracellular signaling cascades upon cellular stimulation by extracellular cues." (PMID 28732488, 2017). "We found, in a limited set of matched normal and tumor specimens, that CNKSR1 expression is elevated in cancer tissue compared to normal uninvolved pancreas tissue." (PMID 28732488, 2017). "Current data suggests that CNKSR1 has multiple roles cancer biology, with some reports demonstrating that CNKSR1 interacts with tumor suppressors and others describe its scaffolding protein interactions as oncogenic." (PMID 28732488, 2017). "To identify cancer cell models that could be used to investigate the role of CNKs in motility, we used RT-qPCR to measure the expression of CNKSR1, 2, and 3 in a panel of 39 human cancer cell lines of diverse origins." (PMID 37322019, 2023). "As for the DNA methylation, the cancers and the corresponding genes with hypermethylation were as follows: BRCA: VWF and ITGB3; COAD: QKI, DUSP9, and CNKSR2; KIRC: CNKSR1; PRAD: VWF, LMNA, and ITGB3; UCEC: ITGB3 and APBBAIP." (PMID 38217548, 2024). "Cancer cell lines originating from same organ often gathered in the same cluster, such as C2 [COAD/READ-STAD-PAAD], a group of digestive system cancers whose common features were the high expression of CNKSR1, FOLH1, ADGRG1, SMAD7, LRATD1 and MVP." (PMID 32874774, 2020). "It is likely that the phosphatase activities of those CNKSR1-bound phosphatases could be controlled through a “non-autoinhibitory” direct interaction with CNKSR1 in other cancer cell lines, instead of SKBR-3 cells." (PMID 34187934, 2021).
tumor (5 papers, 2017 to 2026). "CNKSR1 may help to identify patient subgroups with unfavorable tumor biology in order to improve risk stratification and treatment selection." (PMID 28732488, 2017). "We identified CNKSR1 low patients at high risk for disease progression suggesting that there might be distinct differences in tumor biology between CNKSR1 high and CNKRS1 low tumors." (PMID 28732488, 2017). "Several studies identified specific genes and pathways associated with invasive tumor behavior; for example, ITPKB and CNKSR1." (PMID 39859246, 2025). "Since the unfavorable course of low CNKSR1 expressing tumors suggests a more aggressive tumor biology, we investigated the possibility that the impact of resection on survival was diminished in this group." (PMID 28732488, 2017). "When stratifying primary, non-metastatic tumor biopsies by CNKSR1 expression, resection was associated with improved survival in patients with high CNKSR1 expression (p < 0.0001) but not low CNKSR1 expression (p = 0.3666)." (PMID 28732488, 2017). "This analysis was limited to primary, non-metastatic tumor biopsies, since this represents the group where CNKSR1 status might be used in pre-operative decision-making." (PMID 28732488, 2017).
CNKSR1 also shares sentences with these, for which no sentence is quoted: cervical cancer (1 paper); digestive system cancer (1); hepatocellular carcinoma (1); liver cancer (1); pancreatic adenocarcinoma (1).